SHARPIN (SHANK associated RH domain interactor)
Diseases named in the same sentence as SHARPIN in open-access papers (continued):
Sharing a sentence is not in itself a finding about the gene and the disease.
infection (3 papers, 2016 to 2024). The state of being infected such as from the introduction of a foreign agent such as serum, vaccine, antigenic substance or organism. "Infection of SHARPIN KO A549 cells resulted in increased RIG-I-driven gene activation compared to WT cells, with interferon transcription as well as IRF3 and NF-κB-dependent gene transcription all increased in KO cells." (PMID 38001254, 2024). "Strikingly, infection increased from 17% in WT cells to 25% in the SHARPIN-KO cells (p = 0.0357)." (PMID 38140653, 2023). "Moreover, infection was increased in SHARPIN KO cells and decreased in RNF5 KO cells." (PMID 38140653, 2023). "Together, these results show SHARPIN has an effect on the ORF3-mediated IFN induction, while infection is stimulated in the KO cells." (PMID 38140653, 2023). "Six of these genes were predicted to be involved in host immune response to infection: PTN on BTA4, AP3B1 on BTA10, HSF1on BTA14, SHARPIN on BTA14, TRAF4 on BTA20 and FKBP5 on BTA23." (PMID 26960806, 2016). "At 3 h post-SeV infection, HOIP, SHARPIN and TBK1 could all be found in complex with immunoprecipitated NEMO, enriched compared to mock-infected cells." (PMID 38001254, 2024). "Infection of cpdm MEFs, lacking SHARPIN expression, with SeV resulted in a slight reduction in NF-κB-dependent genes, but increased IRF3-dependent transcription." (PMID 38001254, 2024). "Overall our data adds detail to the significant contribution of LUBAC to antiviral immunity and places HOIP and HOIL-1, but not SHARPIN, as key regulators of the IFN response to infection by RNA viruses." (PMID 38001254, 2024).
myopathy (2 papers, 2016 to 2024). A disease of the muscle in which the muscle fibers do not function properly. "Because Rbck1/HOIL‐1L deficiency leads to destabilization of other LUBAC components including HOIP and SHARPIN, the myopathy symptoms in these patients may derive from the deregulation of linear ubiquitination." (PMID 27702987, 2016).
respiratory system diseases (1 paper, 2021). "One of the two non-synonymous variants in the SHARPIN gene, variant rs34173062 (MAF: 5.7%), has been associated with respiratory system diseases in GWAS." (PMID 34992629, 2021).
SHARPIN also shares sentences with these, for which no sentence is quoted: triple-negative breast carcinoma (2 papers); Arthritis (1); cardiovascular disease (1); chordoma (1); colitis (1); dementia (1); diabetes (1); diffuse large B-cell lymphoma (1); Ductal Breast Carcinoma (1); dyslipidemia (1); eosinophilia (1); eosinophilic esophagitis (1); epithelioid sarcoma (1); fibrosis (1); gastric cancer (1); glioma (1); glycogen storage disorders (1); Hypertension (1); invasive carcinoma (1); invasive ductal breast carcinoma (1); liposarcoma (1); Liver Cirrhosis (1); mastitis (1); metabolic disorders (1); metastatic tumors (1); myocardial infarction (1); nasopharyngeal carcinoma (1); neurodegenerative disease (1); Obesity (1); osteosarcoma (1).
A further 10 diseases each share a sentence with SHARPIN in 1 paper.